C22orf46P (chromosome 22 open reading frame 46, pseudogene )
Synonyms: C22orf46
Gene: Long non-coding RNA gene on chromosome 22 (41,688,877 to 41,698,136, forward strand). Ensembl gene ENSG00000293428.
Diseases named in the same sentence as C22orf46P in open-access papers:
C22orf46P is named in the same sentence as 1 disease in open-access papers, as found by Europe PMC text mining. Sharing a sentence is not in itself a finding about the gene and the disease.
C22orf46P shares sentences with these, for which no sentence is quoted: lymph node metastases (1 paper).